KRAS (KRas proto-oncogene, GTPase)
Diseases named in the same sentence as KRAS in open-access papers (continued):
Sharing a sentence is not in itself a finding about the gene and the disease.
tumor (continued). "SNVs present with allele frequency of ≤ 5% (rare SNVs) occur frequently in genes commonly mutated during cancer (for example, EGFR, KRAS, PIK3CA, and BRAF), and can provide insight into the dynamics of subclonal tumour populations." (PMID 32024475, 2020). "Significant differences were found between KRAS MT and KRAS WT patients among variables of age, race, location, surgery, tumor stage, grade, positive regional nodes amount, and chemotherapy experience (p < 0.05)." (PMID 32547859, 2020). "The KRAS oncoprotein triggers tumor cell growth and survival because it acts as a crucial mediator of intrasellar signaling pathways." (PMID 32560187, 2020). "Recently, Liu’s group showed that a covalent inhibitor specific for G12C mutant KRAS induces tumor regression in in vivo models." (PMID 32486141, 2020). "Tandem peptides combing a CPP with tumor targeting RGD through a disulfide bond complexed with anti-KRAS siRNA formed nanoparticles that significantly delayed tumor growth in a mouse model of pancreatic cancer." (PMID 32138146, 2020). "Although it does not directly inhibit MEK, trametinib has been shown to limit tumor progression via CD8 T‐cell mediated factors by altering signaling along the RAS‐ERK pathway in cancers with KRAS amplification." (PMID 32881420, 2020). "This combination is effective in half of KRAS-mutated NSCLC and cause potent tumor regression in xenograft and PDX models." (PMID 32560574, 2020). "The panel also mimics several aspects of human PDAC, such as subtypes with KRAS amplification, different routes of tumor development, such as chromothripsis, and a wide spectrum of genetic, morphological, and clinical heterogeneity." (PMID 32651227, 2020). "CDX2 loss was associated with right-sided primary tumor, poor differentiation, MSI-H, BRAFmut, and KRAS wild type (KRASwt)." (PMID 32117703, 2020). "Here, our analysis of the correlation between KRAS mutation status and TMB revealed TMB to be associated with tumor immunogenicity and greater benefit of ICI therapy." (PMID 33072585, 2020). "The KRAS (G12C) inhibitor AMG510 drives anti‐tumor activity, and has reached the clinical testing stage in human solid tumors (clinicaltrials.gov identifier NCT03600883)." (PMID 32724874, 2020). "Mechanistically, inhibition of the KRAS signaling cascade impairs glycolysis and mitochondrial function in tumor cells, which enhances the dependence of tumor tissue growth on the products from autophagic degradation." (PMID 32532955, 2020). "On the other hand, mutations of the TGFRB signaling pathway (SMAD2–4 or TGFRB) can frequently occur together with KRAS in this tumor type (~40%)." (PMID 32725342, 2020). "We also detected STAT3 and KRAS being upregulated in the tumor and metastatic tissue of a subset of patients." (PMID 32345963, 2020). "In KRas-induced tumours from PDAC cells, Ser181 phosphorylation was critical for KRas to interact with the heterogeneous nuclear ribonucleoproteins A2 and B1, which was required for PI3K/AKT activation, cell survival and tumour formation." (PMID 32456244, 2020). "Constitutively activated KRAS has several effects on tumor initiation and clinicopathological features, influencing tumor progression, local invasion, and metastasis formation." (PMID 32899322, 2020). "We show that SLIT2, in a ROBO1-dependent manner, negatively impacts the survival of KRAS-transformed cancer cells by inhibiting macropinocytosis, thus limiting protein uptake in a Glut-deprived state similar to the tumor microenvironment found in vivo." (PMID 32807784, 2020). "Additional KRAS analysis of 16 patients showed only 50% concordance between primary tumor tissue and CTCs." (PMID 32471160, 2020).
tumor (continued). "We then analyzed further tumor parts of the stomach on large scale slides and were finally able to secure KRAS amplified clones in the primary tumor in three of the six cases (see discussion)." (PMID 32571252, 2020). "Overexpressed lncRNA-NUTF2P3-001 competitively bound to miR-3923, increasing V-Ki-ras2 Kirsten Rat Sarcoma Viral Oncogene Homolog (KRAS) expression, which resulted in significant improvement of tumor cells survival rate and proliferation." (PMID 32587480, 2020). "These CSC have high sensitivity to OXPHOS inhibitors and when OXPHOS inhibitors are combined with a targeted inhibitor of the KRAS pathway tumor recurrence is blocked." (PMID 32028963, 2020). "We treated the chemotherapy-naive PDX15, which was KRAS wild-type, with cetuximab as a monotherapy, and observed a reduction in tumor burden, consistent with the predicted patient outcome based on clinical criteria for cetuximab treatment." (PMID 32825052, 2020). "Thus, our data suggest that sampling either the primary (pre- or posttherapeutical tumor tissue) or metastatic lesion may be valid for the initial evaluation of KRAS mutation status for predicting the response to anti-EGFR treatment and guiding clinical decisions." (PMID 33002027, 2020). "Tumor tissue collected at diagnosis was available only for one (ID#88) out of 3 KRAS positive patients, and its analysis confirmed the co-existence of EGFR and KRAS mutations (KRAS allelic frequency 13.8%)." (PMID 33520716, 2020). "Other enriched processes in this tumor phenotype included KRAS, a critical regulator of oncogenic properties, cell–cell adhesion, androgen feedback, and stress responses to hypoxia and UV exposure." (PMID 32850353, 2020). "The findings suggest a higher incidence of mutant allele–specific imbalance of the KRAS, EGFR, or PIK3A mutations or presence of subclonal tumor populations harboring IDH1/2 mutations." (PMID 32333643, 2020). "In bone marrow tumor DNA samples, the detection rate of BRAF V600Mx mutations was 4/83 (5%), KRAS Mx was 13/83 (16%), NRAS G12/G13 was 3/83 (4%) and NRAS Q61 was 14/83 (17%), which were approximately equivalent to those found using an NGS method." (PMID 32284750, 2020). "Retroviral transfer of the KRAS-specific TCRs into human T cells conferred KRAS neoantigen-specific anti-tumor activity in vitro and in vivo." (PMID 32117272, 2020). "KRAS plays a major role in two tumor-related cellular pathways, mitogen activated protein kinase (MAPK) and PI3K/AKT, by regulating their activation in response to cellular stimuli." (PMID 32625092, 2020). "Because EMab-17 showed high binding affinity and anti-tumor activity against HCT-15 and HCT-116 cells, we evaluated the ADCC and CDC activities of EMab-17 for CRC cell lines with KRAS p.G13D mutation." (PMID 32839411, 2020). "The protein level of KRAS in tumor tissues (n = 3) was also higher than that in normal tissues (n = 3)." (PMID 33005174, 2020). "The aim of this study was to determine the prevalence, prognostic, and predictive effect of CDX2 loss in unselected patients of mCRC in relation to tumor differentiation, BRAF, KRAS, and MSI status." (PMID 32117703, 2020). "Here, the authors show that the combination of fasting-mimicking diet with vitamin C decreases tumor development and increases chemotherapy efficacy in KRAS-mutant cancer." (PMID 32393788, 2020).
tumor (continued). "We further identified the associated mechanisms by which disruption of the KRAS G12S allele leads to the blockade of the AKT and ERK signaling pathways, thus inhibiting tumor growth." (PMID 32308773, 2020). "In our study, the case where both KRAS and BRAF mutations are identified is a 75-year-old female with a 3 cm tumor in rectum." (PMID 32582557, 2020). "Through these pathways, KRAS modifies cell transformation and inhibits the tumor suppressor pathways." (PMID 32858990, 2020). "We compared the infiltration of immune cells, tumor mutational burden (TMB), HLA gene expression, and checkpoint-related genes between the KRAS-mutated and wild-type samples." (PMID 33254149, 2020). "First, detection of mutant KRAS ctDNA prior to surgery or in the immediate postoperative period predicts a higher likelihood of tumor recurrence and poorer survival." (PMID 33077776, 2020). "Elevated levels of cellular KRAS as a result of codon optimization showed reduced tumor burden in mice." (PMID 32715349, 2020). "Recently, several studies have described the tumor-suppressive effects of their KRAS peptide vaccines in different preventive or therapeutic mouse models." (PMID 32903495, 2020). "Multivariate analysis showed that KRAS mutations, PI3K pathway alterations, and tumor differentiation status were independent factors that have statistically significant influences on clinical outcomes of IMA patients." (PMID 33505917, 2020). "An analysis of 3256 patients with CRC from different clinical trials (QUASAR, FOCUS and PICCOLO) confirmed a higher incidence of HER2-positive CRC in native KRAS/BRAF tumours and advanced stages." (PMID 32418154, 2020). "After examining the RNA-Seq data of CRC patients from the TCGA database using the GEPIA website, we found that PRMT5 expression is in fact strongly positively correlated (p < 0.005, R = 0.81) with KRAS expression in CRC patient tumor samples." (PMID 32731506, 2020). "Specifically, we evaluated each of the 4 common tumor markers (MSI, CIMP, BRAF, and KRAS) separately, as well as 3 pathways of carcinogenesis defined by combinations of those markers and tumor location." (PMID 32923935, 2020). "Oncogenic KRAS enhances immune checkpoint inhibitor efficacy by providing an inflammatory tumor microenvironment." (PMID 33194642, 2020). "Clinical anti-tumor activity was observed with durable tumor shrinkage in KRAS-mediated NSCLC and low-grade ovarian carcinoma." (PMID 32560574, 2020). "We further performed subgroup analysis of KRAS mutation status among different AJCC 7th stages and tumor locations." (PMID 32547859, 2020). "In an earlier report of the analysis of sixteen KRAS mutant primary tumors, a very high discordance rate was detected between samples of different regions of the primary tumor." (PMID 32725342, 2020). "Recent studies indicate that CAV-1 has several other functions beyond protein transport like its role in signal transduction, tumor progression and tumor regression and also that KRAS inhibits MTH1 function through CAV-1." (PMID 31919461, 2020). "In combination with the TNM stage information, KRAS mutations and the MSI status of the tumor are used in clinical practice to determine treatment options." (PMID 31296182, 2019). "Such downregulation of NRP1 in oncogenically KRAS-transformed cells promotes tumor growth by reducing SMAD2 phosphorylation." (PMID 30717262, 2019). "Exosomes isolated from colon cancer cells expressing a mutant form of the protein K-RAS (KRAS) contain the mutant KRAS along with numerous proteins that have the ability to promote tumor progression." (PMID 30923321, 2019).
tumor (continued). "Oncogenic Kirsten rat sarcoma 2 viral oncogene homolog (KRAS) mutations, which occur in over 90% of human PDAC, are the dominant driver for tumor progression and play a critical role in reprogramming metabolism." (PMID 31569510, 2019). "Several studies have incorporated CMS with other molecular features to in order to refine prognostic groups, and have described poorer outcomes in BRAF-mutated CMS1 MSS tumours, and KRAS-mutated CMS2/3 MSS tumours, and favourable outcomes in CMS1 MSI tumours." (PMID 31775679, 2019). "IRE enhanced the immunogenicity of KRAS* tumor by releasing DAMPs, which subsequently induced DC activation." (PMID 30796212, 2019). "In terms of sensitivity and turn-around time, the KRAS StripAssay is more favorable as it is a rapid and sensitive test that can be utilized when few tumor cells are present." (PMID 31877940, 2019). "TEADs play important roles in tumor progression and drug resistance downstream of the hyperactivating mutations on EGFR, KRAS, or BRAF." (PMID 31212916, 2019). "In vivo studies showed nuclear localization in tumor cells, reduction of about 80% of the tumor growth in mice, and reduction of KRAS and BCL-2 protein levels in treated tumors." (PMID 30682828, 2019). "As this study included only those patients who had KRAS and NRAS wild‐type disease based on tumor tissue testing, a comparison of the mutational status in tissue versus ctDNA was not plausible for these genes." (PMID 31350822, 2019). "Consistently, autophagy or ASNS inhibition reduced KRAS-driven tumor cell proliferation, migration, and invasion, all effects rescued by Asn supplementation." (PMID 31998641, 2019). "This is supported by a study from Italy that found that KRAS mutations and HER2/MET amplifications were the most common resistance mechanisms detected in ctDNA and tumor tissue analysis, and that patients with MET amplification had a shorter PFS." (PMID 31824558, 2019). "Conversely, overexpression of MT KRAS in tumor cells harboring wild type (WT) KRAS resulted in an increase of mRNAs for the two cytokines." (PMID 31635338, 2019). "The role of KRAS mutations in promoting tumor growth and its prevalence in PDAC have made KRAS an attractive therapeutic target." (PMID 30759745, 2019). "A key finding in our study was the regulation of KRAS by miR-873, which was shown to exert a tumor-suppressive effect in PDAC and TNBC, both in vitro and in vivo." (PMID 30654191, 2019). "Raf-1-RBD pull-down experiments for KRAS activity were also carried out using total cell lysates isolated from tumor tissues." (PMID 30971271, 2019). "The multiple signalling pathways engaged by mutant KRAS form the foundation for its diverse biological roles in proliferation, survival, metabolism and tumour microenvironment remodelling." (PMID 30833665, 2019). "Univariate analysis by Kaplan–Meier survival analysis and log-rank test was performed using several factors, including age, primary tumour site, histological grade, histological type, KRAS, BRAF, PIK3CA and MSI status." (PMID 31406299, 2019). "She did not carry any germline cancer-associated variants and tumor targeted gene sequencing showed somatic mutations in APC, KRAS, and FBXW7 in the primary tumor sample." (PMID 30850667, 2019). "Tumor volume at the conclusion of the experiment was suppressed in the KRAS siRNA NP group (p<0.01)." (PMID 31413817, 2019). "This suggests that differential dosage of KRAS expression can have contrasting effects on cellular metabolism and highlights the evolution of metabolic states throughout tumor development." (PMID 31681559, 2019).
tumor (continued). "ERK reactivation under MEK inhibition has been reported to be the main problem in therapeutic strategies aimed at NRAS and KRAS mutant tumours, with ERK being the critical node between responsiveness to MEK inhibition and MAPK reactivation." (PMID 31126017, 2019). "A broad approach with a panel of genes should be relevant to detect actionable mutations in other genes than KRAS, NRAS and BRAF and discuss cases in multidisciplinary molecular tumour boards." (PMID 31265477, 2019). "Without any known actionable mutations were detected in the five samples, such as EGFR, KRAS, BRAF, HER2, and EML4‐ALK in the tumor tissues." (PMID 30941903, 2019). "Analysis of the viability shows similar results to those previously observed in 2D culture including a significant increase of anti-tumor effects after dual targeting of miR-21 and KRAS compared to TPN-KRAS alone and combo-NT." (PMID 31523393, 2019). "Tumor organoids were subsequently generated from first passage cancer cells isolated from F1 tumor tissue of PDOX that preserve the epithelial cancer characteristics and KRAS mutations of primary tumors." (PMID 31572675, 2019). "A total of 61 patients with KRAS exon 2 wild-type CRC tumours were enrolled between July 2009 and June 2012 and received a median of 78 days of treatment (range, 1–279)." (PMID 31363167, 2019). "HOXA5 methylation was associated with age, T, M, stage, and tumor status, and HOXA6 methylation was associated with age and KRAS mutation." (PMID 31165042, 2019). "By contrast, for oncogenes (orange) with variants highly concentrated at hotspots, particularly KRAS, BRAF, IDH1, the probability of encountering new variants in future tumor samples tends to be low." (PMID 31796730, 2019). "The median MAFs of KRAS in ctDNA and tumor tissue were 0.34% (range: 0–34.71%) and 2.81% (range: 0–66.10%), respectively." (PMID 31850201, 2019). "We show that ablation of EGFR significantly suppressed tumor growth in KRAS-dependent cells and induced significantly higher expression of CX chemokine receptor 7 (CXCR7) and activation of MAPK (ERK1/2)." (PMID 30935067, 2019). "The iRGD-tumor-penetrating nanocomplexes (iRGD-TPNs) with polyethylene glycol (PEG)-peptide conjugates delivering anti-KRAS siRNA to tumor sites significantly delayed tumor growth in murine models." (PMID 31346334, 2019). "Four proteins were found differentially expressed in KRAS-mutant as compared to wild-type tumours (overexpressed in mutant: KRAS, EGFR; overexpressed in wild-type: TOPO1, TOP2A)." (PMID 31537838, 2019). "The KRAS wild-type tumor group had a 16% increase in overall response rate (ORR) to 60% when cetuximab was added to FOLFIRI but there was a 4% decrease in response to 36.2% among KRAS mutated tumors." (PMID 30646508, 2019). "Genetic deletion of Keap1 or overexpression of its target, the anti-oxidant master regulatory transcription factor NRF2, accelerates KRas-driven LuAd in mice, suggesting that excessive oxidative stress limits tumour progression." (PMID 31032816, 2019). "Because the distinct genetic alteration between RCC and LCC, both of the location of tumor and KRAS status are proposed to influence the prognostic value CRC." (PMID 30917791, 2019). "KRAS is frequently mutated or dysregulated in CRC and it is involved in the modulation of downstream effectors Rac/Rho to promote tumor metastasis." (PMID 31110467, 2019). "This underlines the need to not only discriminate the MSI status of a tumor in any classification, but to also include information on the BRAF and KRAS mutational status." (PMID 31296182, 2019).